ARID1A (AT-rich interaction domain 1A)
Diseases named in the same sentence as ARID1A in open-access papers (continued):
Sharing a sentence is not in itself a finding about the gene and the disease.
tumor (continued). "The involvement of ARID1A in cancer progression is known to regulate the PI3K/AKT pathway associated with cancer cell growth, proliferation, and migration as well as a tumor suppressor role." (PMID 34063990, 2021). "Most of the included studies (28/29, 96.6%) suggest that ARID1A serves as a tumor suppressor in CCA." (PMID 34249744, 2021). "For example, high expression of SMARCD1, SMARCA4 and ARID1A can promote tumor cell proliferation and invasion, accompanied by poor survival." (PMID 34937564, 2021). "As a result of ARID1A’s function as a tumor suppressor, it is of special interest to determine how the function of SWI/SNF complexes is perturbed following loss of this subunit." (PMID 34731603, 2021). "This 1p36 syntenic deletion, which included the Arid1a and Chd5 tumor suppressors, resulted in increased anchorage independent growth and defects in differentiation." (PMID 34885007, 2021). "Arid1a inactivation is correlated to worse prognosis and poor tumor differentiation and its conditional ablation in a KRAS-driven PDAC murine model accelerated significantly invasive tumors formation, a finding underlying its tumor suppressor potential." (PMID 34771695, 2021). "As an explicatory model, preliminary literature data showed that ARID1A alterations increase tumor cell sensitivity to agents targeting the ATR protein, EZH2 or the PI3K pathway." (PMID 33641055, 2021). "It suggested that ARID1A and EZH2 are a pair of important molecules in maintaining the balance of the proliferation and apoptosis of cells while ARID1A serves as the tumor suppressor." (PMID 34715776, 2021). "We found that ARID1A is significantly downregulated in COAD tumor malignant than adjacent normal tissues." (PMID 34414106, 2021). "ARID1A is thought to play a significant role both in tumor initiation and in tumor suppression, which is highly dependent upon context." (PMID 34671561, 2021). "Loss of expression of proteins involved in chromatin remodeling, such as ARID1A, was observed only in MMRd HG-CRCs, which also showed more frequently PD-L1 expression and a higher number of tumor infiltrating lymphocytes." (PMID 33435234, 2021). "It is also considered to have a role in epigenetic modulation in tumor biology, as evidenced by the synthetic lethality of EZH2 inhibition in ARID1A‐mutated tumors." (PMID 33350171, 2021). "We next compared the relative gene expression of immune related genes between ARID1A mutant compared to ARID1A wild-type tumours." (PMID 34359755, 2021). "In some cases, synthetic lethality is caused by the concomitant knockout of two mutually exclusive paralogues: Tumours with a SMARCA4 deficiency are sensitive to SMARCA2 depletion, and ARID1B is required for survival of ARID1A-mutant cancers." (PMID 33941852, 2021). "The tumor suppression mechanisms of ARID1A interplay with other oncogenic pathways and affect the proliferation and growth of cancer cells." (PMID 34671561, 2021). "The study cohort consisted of 56 SWI/SNF‐deficient DDEC/UEC (2 POLE‐mutated), which showed either SMARCA4 (BRG1) loss, ARID1A/1B co‐loss, or SMARCB1 (INI1) loss in the undifferentiated tumor, and 26 SWI/SNF‐intact DDEC/UEC (4 POLE‐mutated)." (PMID 33125840, 2021). "We initially used gross histological assessment of immune infiltrate and distribution using the Salgado scoring system in 31 primary OCCC tumours and correlated TILs with FIGO tumour stage, clinical risk status and ARID1A mutation status." (PMID 34359755, 2021). "ARID1A depletion supports the adrenergic-to-mesenchymal transition by regulating enhancer-mediated gene expression, thus promoting cell invasion and tumour resistance to chemotherapy." (PMID 34884690, 2021).
tumor (continued). "Based on the current evidence, ARID1A variation is expected to solely play a tumor suppressor in the tumorigenesis of multiple cancers, including CCA." (PMID 34249744, 2021). "They further established the chemically induced murine HCC models and found that Arid1a advances tumor initiation through cytochrome P450 (CYP450)-mediated oxidative stress, which provides with the possible mechanisms underlying tumor induction by ARID1A." (PMID 34671561, 2021). "And in-vivo interference of CCNE1 showed a suppressive tumor growth effect on an ARID1A mutant TOV-21G xenograft mouse model." (PMID 34070839, 2021). "Recent molecular mechanistic research has revealed that ARID1A participates in tumor progression through its effects on control of cell cycle, modulation of cellular functions such as EMT, and regulation of various signaling pathways." (PMID 34671561, 2021). "POLE, BLM, ARID1A and APC genes were mutated within a tumor that originated within the temporal lobe, but for this gene the highest expression was in the midline structures as opposed to temporal lobe." (PMID 34257334, 2021). "ARID1A correlates with some clinicopathological parameters, including age, gender, tumor stage, pathological stages, and tumor purity." (PMID 34414106, 2021). "The ARID1A expression was significantly increased in tumor tissues (P < 0.05) consistent with the TCGA database." (PMID 33558447, 2021). "Otherwise, ARID1A acts as a proximal tumour suppressor, promoting tumorigenesis via MYCN amplification in tumours harbouring larger 1p36 deletions." (PMID 34884690, 2021). "In this review, we synthesize a mechanistic understanding of the role of ARID1A in human tumor initiation as well as in tumor suppression and further discuss the implications of these new discoveries for potential cancer intervention." (PMID 34671561, 2021). "Consistent with its proposed tumor suppressor effect, the re-expression of ARID1A in the OCCC cell line OVISE with ARID1A mutations resulted in growth inhibition." (PMID 34659566, 2021). "It has been proven that ARID1A alterations indicated improved prognosis of tumor patients for compromising MMR and enhancing the infiltration of lymphocytes." (PMID 34901000, 2021). "Under different circumstances, ARID1A plays a specific role in tumor initiation or tumor suppression." (PMID 34671561, 2021). "Recently, proof was provided for the context-dependent tumor-suppressive and oncogenic roles of ARID1A in the liver cancer." (PMID 34805154, 2021). "Their analysis of different candidate 1p36 tumor suppressor genes, such as Arid1a, Chd5, Camta1, and Kif1b, identified Arid1a as the gene with strongest correlation between expression levels and time to tumor onset." (PMID 34885007, 2021). "We noticed that there is a possible relationship between ARID1A high expression and tumor microenvironment infiltrating immune cells." (PMID 34414106, 2021). "The mutational profile of the CTNNA1 germline mutated tumour encompassed somatic mutations in RHOA, a specific DGC and PCC‐NOS gene, and in ARID1A and PIK3CA, genes transversally mutated in both DGC and IGC." (PMID 33724653, 2021). "Univariate analysis of OS was performed using Cox regression analysis to determine ARID1A expression (p=0.027), Her-2 status (p=0.002), Tumor size (p=0.026) and LNM (p=0.018) as significant prognostic predictors." (PMID 33592583, 2021). "ARID1A alterations or expression loss leads to the advantage of EZH2 function and result in the excessive proliferation of tumor cells." (PMID 34715776, 2021).
tumor (continued). "Increased ARID1A facilitates tumor initiation via oxidative stress mediated by CYP450, and decreased ARID1A in established tumors strengthens metastasis because inhibitory factors present lower expression." (PMID 33771191, 2021). "The loss of the tumor-suppressor gene AT-rich interaction domain A (ARID1A), a multidrug resistance-associated protein 2 (MRP2) regulator, has been shown to lead to a platinum-resistant phenotype in a preclinical tumor model." (PMID 33916221, 2021). "Our data encourages the development of new therapies against ARID1A mutations and epigenomic methylation when involved in MSI neoplasms." (PMID 33608032, 2021). "ARID1A deficiency impairs MMR efficiency and causes a mutator phenotype in both cancer cell lines and in vivo tumor samples." (PMID 33419967, 2021). "NUCOLL43, a novel OCCC cell line derived from an ARID1A-positive tumor, also exhibited intact DNA HR capacity." (PMID 34737943, 2021). "Droplet Digital PCR technology validated the ARID1A mutation and the FGFR2 amplification in bulk tumor DNA and in longitudinally collected ccfDNAs at three different time points of disease evolution." (PMID 34178989, 2021). "ARID1A is involved in the modulation of various cellular processes that are vital in preventing tumor initiation and progression via regulating the downstream transcriptional activity of several proto-oncogenes and tumor suppressor genes (TSGs)." (PMID 34924820, 2021). "ARID1A and PBRM1 encode a subunit of the SWI/SNF complex, and were mostly mutated in CCA, including association with tumor progression." (PMID 34070951, 2021). "It is important to mention that miR-31 and ARID1A are found to be antagonistic in tumor cells, wherein the ARID1A gene is inhibited, thus promoting differentiation of stem cells into cancerous cells." (PMID 34946938, 2021). "Besides, ARID1A alterations or expression loss could contribute to the resistance to EGFR-TKIs via a variety of pathological process during tumor development, including epithelial to mesenchymal transition (EMT), angiogenesis of tumor and the inhibition of apoptosis." (PMID 34715776, 2021). "Despite this evidence, the role of ARID1A in cancer is still not fully understood, with some studies suggesting a tumor suppression role, while a few others indicate an oncogenic function." (PMID 33748136, 2021). "In particular, for each of the well-studied tumour suppressors ARID1A, SMARCA4 and PTEN the most significant robust synthetic lethal interaction we identified has previously been reported in the literature." (PMID 32463358, 2020). "Herein, patients with higher ARID1A and ANXA1 expressing tumours showed increased recurrence risk and a higher risk of dying from this disease." (PMID 33276477, 2020). "Several papers discuss possible therapeutic interventions, for example, by targeting the role of ARID1A in regulating DNA damage checkpoints at double strand breaks, which sensitize tumour cells to PARP inhibitors." (PMID 31906887, 2020). "We found that decreasing ARID1A immunoreactivity in Ov-CCA and loss of ARID1A was associated with tumor metastasis." (PMID 33344089, 2020). "The ARID1A involvement in cell-cycle arrest shows that it significantly aids tumor repression, through the SWI/SNF complexes." (PMID 32334542, 2020).
tumor (continued). "The results were correlated to clinical and pathological tumor characteristics as well as to the expression of ARID1A and β-Catenin." (PMID 32388637, 2020). "Since ARID1A loss seems to be associated with advanced tumor stages, we focused on this important SWI/SNF component with therapeutic potential to confirm that ARID1A protein loss results from genetic ARID1A gene alterations." (PMID 33227989, 2020). "In CCC-1, the VAF of ARID1A was 26.8% in the tumour and 27% in the organoid, which indicates that a subclone was maintained in the organoid culture." (PMID 32724113, 2020). "In the present study, the mechanism of tumor suppression by ARID1A was investigated using high-throughput platform data obtained from the TCGA portal." (PMID 32878261, 2020). "There is strong evidence that tumours with altered ARID1A represent a biologically relevant tumour subgroup of EACs." (PMID 31906887, 2020). "ARID1A participates in directing at least 3 processes relevant to tumor suppression: proliferation, differentiation, and apoptosis." (PMID 32393201, 2020). "Among the four subtypes, EBV-positive tumor was associated with mutations in PIK3CA and ARID1A genes and elevated PD-L1 expression." (PMID 32824568, 2020). "Our mutational analysis shows that ARID2 is a highly mutated SWI/SNF subunit surpassing the mutation frequency of ARID1A, which is the subunit that is the main mutated SWI/SNF subunit in other tumor types." (PMID 33321963, 2020). "Current evidence on the importance of ARID1A shows that this gene acts as a tumor suppressor, and plays a key role in the progression of many types of cancer." (PMID 32334542, 2020). "Taken together, ARID1A expression is required for the initial tumour development and the suppression of HCC metastatic potential, depending on the cellular and temporal contexts during HCC progression." (PMID 32162380, 2020). "In this context it is interesting to note that alterations of ARID1A are already found in precursor lesions of EAC (Barrett’s dysplasia), and here we show a mostly homogeneous loss of ARID1A in the tumour." (PMID 31906887, 2020). "Reportedly, the AT-rich interactive domain-containing protein 1A (ARID1A) is located in the chromosome 1p36 region acting as a tumor suppressor gene." (PMID 32596229, 2020). "Not surprisingly, we find that the 105C mutational profile matches that of many OCCC cell lines and human tumor samples with respect to the ARID1A, PIK3CA, and PTEN genes." (PMID 33153119, 2020). "One tumour showed a disrupting mutation and LOH of ARID1B and two tumours each harboured two truncal mutations in ARID1A, which are all members of the SWI/SNF-chromatin-modifying complex." (PMID 31949146, 2020). "Our observation with established HCC agrees well with their results, supporting the idea that ARID1A has tumor suppressor activity in the later stage of HCC." (PMID 32878261, 2020). "Given the important functional roles of ARID1A, better understanding of how ARID1A inactivation contributes to tumor development is critical to improve treatment in ARID1A mutated cancers." (PMID 32483112, 2020). "In turn, confirmation of such a role would corroborate a recent study showing that hepatic Arid1a can harbor either a tumor suppressor or oncogenic role depending on the cellular context." (PMID 33084574, 2020). "We observed heterogeneous distribution of ARID1A in 4.8% of the tumours, heterogeneous distribution of BRM in 9.6% of cases and heterogeneous distribution of BRG1 in 0.6% of the EACs." (PMID 31906887, 2020).
tumor (continued). "ARID1A alterations would compromise mismatch repair pathway and increase the number of tumor-infiltrating lymphocytes and PD-L1 expression in some cancers, which would cooperate with immune checkpoint inhibitors (ICIs) treatment." (PMID 31949479, 2020). "Although inactivating mutations were only seen in ARID1A and ARID1B genes, IHC only confirmed loss of ARID1B in VOA1066 primary tumor and cell line." (PMID 33052929, 2020). "In humans, the 16 SWI/SNF complexes are a class of nucleosome remodelers, and ARID1A, an epigenetic tumor suppressor, is a member of mammalian 17 chromatin remodeling complex, SWI/SNF." (PMID 31731647, 2019). "In contrast to its tumor-promoting activity during tumor initiation, deletion of Arid1a accelerated HCC tumor progression and metastasis in late stage of HCC development, further indicating the complicated roles for Arid1a in HCC development." (PMID 31731480, 2019). "ARID1A, a component of the SWI/SNF complex, is a tumor suppressor with a high frequency of inactivating mutations in many cancers and plays an important role in targeting the complex to gene promoters." (PMID 31210753, 2019). "While alterations in SWI/SNF composition have wide-spread roles in tumor biology, these findings describe a very confined and specific vulnerability of the residual SWI/SNF complex in cancers containing inactivating ARID1A mutations." (PMID 31796878, 2019). "The defective telomere cohesion is selective against genomic instability caused by ARID1A inactivation during mitosis to balance the need to proliferation and the tumor suppressive function of ARID1A in preserving genomic stability." (PMID 31492885, 2019). "Studies in mice and cell lines have demonstrated that ARID1A is a tumor suppressor that represses KRAS-induced precancerous lesion formation and suppresses ductal proliferation." (PMID 31769422, 2019). "The AT-rich interactive domain 1A (SWI-like) gene (ARID1A), which encodes the protein BAF250, a key component of the SWI/SNF complex, is usually described as a tumor suppressor." (PMID 31847141, 2019). "Adenine-thymine (AT)–rich interactive domain-containing protein 1a (ARID1a) is a tumor suppressor gene." (PMID 30811493, 2019). "ARID1A encodes for BAF250a subunit of the SWI/SNF complex and has been shown to be a bona fide tumor suppressor based on several mutational and functional studies." (PMID 31056726, 2019). "Regardless, our findings support the notion that ARID1A exerts its tumor suppressor function by preserving genomic stability through eliminating cells with severe genomic instability during mitosis when it is inactivated." (PMID 31492885, 2019). "ARID1A is the most frequently mutated member of the SWI/SNF family and high incidence of inactivating mutations in varied cancers along with emerging functional studies postulate ARID1A as a novel tumor suppressor." (PMID 30858552, 2019). "Arid1a protein is thought to influence transcription factor associations with the SWI/SNF complexes, and was recently postulated to act as a tumor suppressor and a driver gene in PDAC." (PMID 31480737, 2019). "The critical activity of Arid1a in tumor initiation appears to be related to its transcriptional regulation of the CYP450 family, which oxidizes metabolites and generates ROS in hepatocytes." (PMID 31731480, 2019). "ARID1A mutations were most commonly seen in the MSI tumours in the ACRG study (44.2%), and ARID1A protein loss was also frequent in the approximated ACRG MSI subtype (10/22, 45.5%)." (PMID 31790410, 2019).